APOE (apolipoprotein E)
Diseases named in the same sentence as APOE in open-access papers (continued):
Sharing a sentence is not in itself a finding about the gene and the disease.
infection (continued). "Anti-ApoE Abs specifically co-immunoprecipitated the Zika E protein, demonstrating an interaction between the ApoE and Zika E proteins in infected HMC3 cells 48 h post-infection." (PMID 35902969, 2022). "Further, the combination including four validated indexes and two classical infection indexes for septic diagnosis had the highest AUC‐ROC of 0.772, which was significantly better than that of ApoC3, VCAM1, and ApoE respectively, besides B2M." (PMID 34825737, 2022). "Ad-SIRT3 infection in response to 1 mM NEFA incubation significantly increased the mRNA abundance of MTP, ApoB100, and ApoE, and raised VLDL contents in the supernatants." (PMID 34208809, 2021). "This was confirmed at the protein level, as infection decreased the amount of secreted AHSG and apolipoproteins APOA1, APOE and APOH, in both HepG2 and Huh7 conditioned media, as well as of APOB, APOC3 and SERPINF2 in Huh7." (PMID 34858876, 2021). "The competition by apoE and several viruses to combine with HSPG suggests that apoE is capable of anti-infection activity." (PMID 32306242, 2020). "The assembly, release, infection and immune evasion of HCV can be modulated inside or outside of hepatocytes by the binding or utilization of the host ApoE." (PMID 31027190, 2019). "Therefore, our finding that HIV-1 up-regulates ApoE expression, which in turn limits viral spread by inhibiting Env expression, may help understand the molecular basis by which macrophages can maintain the long-term persistent infection of HIV-1." (PMID 30496280, 2018). "We also observed that EZH2 infection reduced ABCA1 mRNA and protein levels in mouse peritoneal macrophages (MPM), aortas, hearts, livers and kidneys of apoE−/− mice." (PMID 27295295, 2016). "As seen in infection with HCVcc (JFH1), expression of ApoA1, ApoA2, ApoC1, ApoC2, ApoC3 and ApoE enhanced the formation of infectious particles of TH/JFH1 and S310/JFH1 chimeric viruses." (PMID 25502789, 2014). "Since it was clear that the HSPG-BD of apoE was critical for HCV infection, we examined liver-expressed HSPGs for their contribution in mediating infection." (PMID 24751902, 2014). "We measured the mRNA levels of apolipoproteins such as ApoA, ApoB and ApoE in the heart and WATs of mice fed a HFD and RD during infection." (PMID 25275627, 2014). "Our initial studies confirmed that, like other LXR target genes such as ApoE and ABCA1, AIM MФ mRNA expression was induced in response to infection." (PMID 24223991, 2013). "However, PMNs infiltrating the brain of Rag1–/– mice exhibited a mix of proinflammatory (LCN2, APOE) and antiinflammatory (WFDC21, RETNLG) molecules that was most prominent at day 7 after infection along with enhanced PD-1/PD-L1 pathway expression." (PMID 39989461, 2025). "Interestingly, MHV68 titers were decreased in ApoE-/- macrophages at both high and low multiplicities of infection (MOI), indicating that ApoE expression by macrophages supports MHV68 replication." (PMID 40439406, 2025). "APOE isoforms, because of their natural aggregation properties, show potential as therapeutic agents against Gram-negative bacteria and endotoxins during infections." (PMID 39880097, 2025). "Therefore, APOE plays a crucial role in determining the consequences of infection with the pathogen, strengthening the belief that HSV-1 and APOE-ε4 are an important pair of factors in AD." (PMID 39224577, 2024). "Furthermore, the receptor binding domain of ApoE interferes with viral attachment and infection by P. aeruginosa, S. aureus, HSV-1 and HSV-2, with synthetic ApoE peptides having been developed with various antibacterial and antiviral activities." (PMID 39416952, 2024).
infection (continued). "In other words, APOE was only differentially expressed in hematological tumor patients with SARS-CoV-2 infection and was significantly highly expressed in acutely deceased patients compared to patients with normal or long infection." (PMID 38752789, 2024). "Intriguingly, several circulating serum proteins (e.g., ApoE) may adsorb specific SARS-CoV-2 peptides and alter their infection ability by mediating the ACE2 receptor." (PMID 36531241, 2022). "A complement effect on homeostasis during infection is determined by both cytotoxic (activate complement component 5 (C5a) terminal cytotoxic complex (TCC)), and cytoprotective elements (complement factor H (FH), as well as apolipoprotein E (ApoE))." (PMID 35953544, 2022). "We observed an infection induced increase in mitotracker fluorescent intensity in monocytes from male ApoE-/- mice on HFD, but not from females." (PMID 33417618, 2021). "APOE and SPP1 restrict HIVGKO infection in both Jurkat T cells and primary CD4+ T cells." (PMID 33504604, 2021). "The authors, however, seemed unaware that APOE modulates the consequences of infection in a number of infectious diseases, not just in the cited protective action of ε4 in HCV-infection of liver." (PMID 34205498, 2021). "Furthermore, synthetic peptides composed of 18 and 21 amino acids that were derived from the ApoE N-terminal RBD blocked HCV attachment and infection." (PMID 34205894, 2021). "In order to confirm that infection induced enhanced oxygen consumption and spare respiratory capacity was not confined to the ApoE-/- genetic background, we assayed exogenous palmitate respiration in BMDM from IL4RFl/FlCreneg mice." (PMID 33417618, 2021). "Conversely, we looked at whether the DE genes identified in HAM (besides APOE, a well-known DAM gene) showed consistent trends in mouse models of neurodegeneration, infection, and aging." (PMID 32610143, 2020). "ApoE−/− mice were fed either a high-fat Western diet (HFD) or normal chow diet for 10 days before infection with S. mansoni, whereas controls were sham-infected." (PMID 30483256, 2018). "Finally, we created a Vero cell line that expressed the essential factors miR-122, SRBI, and ApoE; the entire HCV life cycle, including infection, replication, and infectious virus production, was completed in these cells." (PMID 27302754, 2016). "It is noteworthy that Wilson's group showed that an ApoE-mimetic peptide, termed COG112, attenuates colon inflammation in response to infection with Citrobacter rodentium or treatment with dextran sulfate sodium salt (DSS) in cells and animals with normal levels of ApoE." (PMID 27538678, 2016). "In addition, the APOE knockout mice had slightly, but significantly lower oocyst shedding per milligram of stool (p<0.05) than APOE3/3 TR mice at days 1 and 3 post- infection, when the oocyst burden in stool was higher." (PMID 24586873, 2014). "Although RNA replication and infectious particle formation in B-KO cells upon infection with HCV were comparable with those in parental Huh7 cells, E-KO cells exhibited slight reduction of particle formation, and the expression of ApoE in E-KO cells rescued infectious particle formation." (PMID 25502789, 2014). "APOE is not a mere cholesterol transporter and is thought to play further roles in tissue repair, immunity, inflammation, and infection." (PMID 24656052, 2014). "No influence of APOE Ɛ4 on successful Plasmodium liver cell invasion was detected by multiplicity of infection." (PMID 24116184, 2013). "Furthermore, it appears that the physiological concentration of apoE may be regulating a delicate balance point between sufficient systemic inflammation to clear the invading pathogen, yet insufficient to harm the host in the process of eradicating the infection." (PMID 20953368, 2010).
infection (continued). "We found that all biomarkers increased with age except Αβ42/Αβ40, regardless of apoE genotype, and that HHV seropositivity was associated with a significantly steeper age-related increase in these biomarkers compared to those without prior infection." (PMID 40664837, 2025). "Virus entry efficiency was not affected when cells were exposed to ApoE prior to infections." (PMID 40295730, 2025). "However, the establishment of latent MHV68 reservoir at 16 days post-infection was not affected by the ApoE genotype of the mice in this study." (PMID 40439406, 2025). "In particular, APOE is involved in both lipoprotein remodeling and blood coagulation, and APOE was also differentially expressed when we compared SARS-CoV-2-infected samples of hematological tumor patients who suffered from normal infection, long infection, and acute death." (PMID 38752789, 2024). "Since Aβ, Tau, ApoE, and LL-37 can be synthesized by neurons, they represent an array of oligmerization-based antimicrobial tools that can be (re-)appropriated to confer a broad defense against multitaxonomic infections in non-immune specialized cells." (PMID 39416952, 2024). "However, Lv-AI662270 infection had no statistically significant influence on lipid profiles and TG in ApoE−/− mice fed with CD." (PMID 36755320, 2023). "The increased mRNA levels of apolipoprotien E (ApoE) and lipoprotein lipase (LPL) observed in Cpn-infected astrocytes relative to uninfected cells at 6 hpi may therefore be necessary to allow Cpn to initiate infection within the astrocyte host." (PMID 30786875, 2019). "Significantly less induction of pro-inflammatory cytokines, TNF-α, IL-6, IL-1β and MCP-1, was found at various time post-infection in ApoE−/− mice; whereas anti-inflammatory cytokine IL-10 was not affected, and IL-12 production was not detectable during infection." (PMID 23977160, 2013). "Interestingly, we observed the expression level of APOE might not only have an effect on TMCs but also on macrophages via the CXCL signaling pathway, which functioned in inducing inflammatory chemokines and migration of immune cells during infection or injury." (PMID 38366188, 2024). "All of these genes except APOE and IL1RL1 have been associated with the regulation of fibrosis and variation in these may regulate risk of pathology irrespective of intensity of infection." (PMID 33659002, 2021). "Importantly, the ApoE−/− mice also had increased levels of IL-12p70 without infection." (PMID 27647324, 2016). "Thus, no influence of ApoE on binding and entry of the internalized HSV1 is expected for the single infection cycle case (MOI 10) and for the first round of infection of the multiple cycle case (MOI 0.1)." (PMID 40295730, 2025). "The mRNA levels of PPAR target genes associated with adipocyte differentiation, including ADRP, FABP4, CD36, APOE, APOC1, ASCL1, were strongly induced in THP-1 cells at 6 or/and 48 h after infection by M. leprae but not stimulation by dead M. leprae, as showed by real-time PCR." (PMID 33075048, 2020). "An interesting report showed that in systemic post-surgical inflammation, whether accompanied by infection or not, HDL was decreased and depleted in both apoA1 and apoC1, but enriched in apoE." (PMID 31779116, 2019). "Indeed, our data support the notion that MVA infection stimulates non-specific palmitoylation of NS4B and ApoE." (PMID 25740959, 2015). "Importantly, the negative control ApoE was also found to be profoundly palmitoylated in the latter condition, suggesting a strong influence on protein palmitoylation by MVA infection." (PMID 25740959, 2015).
infection (continued). "Interestingly, despite the decreased expression of MHV68 lytic genes starting at 24 hours post-infection, the accumulation of MHV68 DNA was not altered in ApoE-/- macrophages, suggesting that ApoE facilitates MHV68 lytic replication downstream of viral DNA synthesis." (PMID 40439406, 2025). "IL-12was depleted in the ApoE−/− mice throughout infection with P. berghei ANKA to determine if the increased levels of this cytokine contributed to protection, but the incidence of ECM was not significantly altered in the IL-12-depleted ApoE−/− mice (data not shown)." (PMID 27647324, 2016).
neurological diseases (96 papers, 2006 to 2025). "Apolipoprotein E (ApoE), predominantly expressed in astrocytes in central nervous system, exists in three ApoE isoforms (ApoE2, ApoE3, and ApoE4) in humans, with ApoE4 linked to increased susceptibility to neurological diseases." (PMID 40375206, 2025). "The apolipoprotein E (APOE) ε4 allele is implicated in cerebrovascular, mental, and neurological disorders but stands as the primary genetic susceptibility factor for AD, and also increases the severity of neuropathology in DLB." (PMID 38390593, 2024). "The apolipoprotein E (APOE) gene lies in chromosome 19 containing three polymorphic alleles, namely ɛ2, ɛ3, and ɛ4 and the ɛ4 allele (APOE4) is involved in amyloid plaque deposition playing a major role for AD and other neurological disorders." (PMID 36827351, 2023). "The APOE gene polymorphism is associated with the risk of the development of several neurological disorders." (PMID 37763074, 2023). "As an allele of ApoE, ApoE-ε4 is not only the biggest genetic risk factor for AD but also related to a variety of neurological diseases." (PMID 35317127, 2022). "In post-industrial settings, apolipoprotein E4 (APOE4) is associated with increased cardiovascular and neurological disease risk." (PMID 34586066, 2021). "Apolipoprotein E (apoE) is the major apolipoprotein in the CNS and predisposes patients to a favorable outcome of neurological disorders." (PMID 31607842, 2019). "Early reports of ApoE deficient mice showed increased vascular permeability in the brain lending credence to the importance of ApoE in neurological disorders." (PMID 25919366, 2014). "Since ApoE4 is linked to multiple neurological diseases, we examined whether ApoE4 mice exhibit different pain sensitivity compared to other ApoE isoforms after nerve injury." (PMID 40375206, 2025). "ApoE isoforms correlate with varied susceptibilities to neurological diseases." (PMID 40375206, 2025). "Further, increased levels of cortisol in APOE-є deficient mice suggest that APOE genotype may influence cortisol concentrations in neurological disorders such as AD." (PMID 36950689, 2023). "Our results suggest that a more complete genotyping in this chromosomal region may help to elucidate more of the crucial roles of the APOE locus variants on cardiometabolic and neurological disorders." (PMID 36011277, 2022). "The deficiency of apoE4 lipidation suggests that increasing the lipidation of apoE in general may be a viable therapeutic avenue for AD and other neurological disorders." (PMID 32882843, 2020). "Our results suggest that rapid brain aging and APOE ε4 are synergistic risk factors, and interventions that slow aging may substantially reduce risk of neurological disease and decline even in the presence of APOE ε4." (PMID 31133613, 2019). "The APOE variants have been implicated in neurological disorders of the central and peripheral nervous system, yet results on their role as a risk or protective factor in DPN have also been inconsistent and a recent meta-analysis could not establish a definite association." (PMID 26074879, 2015). "A focused examination of six AD-related genes – APOE, APP, BIN1, CLU, MAPT and PSEN1 – and SMARCA5, which has been linked to neurological disorders, revealed different expression patterns across cell types and AD." (PMID 41255979, 2025). "The neuroprotective effects of exogenous apoE mimetic peptides have now also been demonstrated in several models of neurological disease including spinal cord injury." (PMID 38545108, 2024). "On the other hand, substantial literature has reported that the ApoE gene was characterized for its impact on lipids metabolism, neuronal function, as well as in the development of certain pathogenesis of neurological diseases." (PMID 35351068, 2022). "We find that genes implicated in neurological diseases have high CNCR density, including APOE, highlighting an unannotated intron-3 retention event." (PMID 33824317, 2021).